MMP9 (matrix metallopeptidase 9)
Diseases named in the same sentence as MMP9 in open-access papers (continued):
Sharing a sentence is not in itself a finding about the gene and the disease.
nephritis (9 papers, 2009 to 2025). Inflammation of renal tissue. "The mRNA expression of MMP-9 in the glomerulus was also increased during the development of anti-GBM nephritis in WKY rats." (PMID 41341833, 2025). "We discovered that hsa-miR-6516-3p contributes to an increase in the expression of MMP9, which is a factor that exacerbates nephritis, via the suppression of its endogenous inhibitor RECK." (PMID 40045202, 2025). "Other biomarkers such as matrix metalloproteinase 9 (MMP-9), red blood cell distribution width, pentraxin 3, alpha-smooth muscle actin, and c-Met were also reported to be associated with the risk of nephritis in IgAV/HSP." (PMID 30154798, 2018). "For each parameter, it was difficult to determine correlation between e.g. Dnase1, MMP2 or MMP9 mRNA levels with age in individual mice since nephritis developed at different time points in different mice." (PMID 20041189, 2009). "The docking results between the targets of VEGFA and MMP9 and each component were also good, which may play an essential role in preventing as well as treating nephritis." (PMID 36998608, 2023). "Besides, serum level of HOTAIR had a significantly positive correlation with IL-6 (r = 0.675, P<0.0001), MMP-9 level (r = 0.757, P<0.0001), proteinuria (r = 0.287, P = 0.035) and grades of nephritis (r = 0.296, P = 0.024)." (PMID 35972968, 2022). "Furthermore, HOTAIR expression level had significantly positive correlation with IL-6 (r = 0.578, P<0.0001), MMP-9 level (r = 0.762, P<0.0001), nephritis grades (r = 0.296, P = 0.024) and proteinuria (r = 0.287, P = 0.035)." (PMID 35972968, 2022). "The serum MMP-9 level and enzymatic activity negatively correlated with serum creatinine and ANCA positivity, which usually means severer nephritis." (PMID 41341833, 2025). "The key targets such as TNF, VEGFA, PTGS2, MMP9, and MAPK1 are directly or indirectly related to the 7 phenolic acids and multiple nephritis-related pathways." (PMID 36998608, 2023). "The protein interaction analysis network showed that TNF, VEGFA, PTGS2, MMP9, MAPK1, and other proteins were the key targets of the 7 phenolic acids in the treatment of nephritis." (PMID 36998608, 2023). "BW mice were sacrificed approximately every second week (in sets of 3) until development of end-stage lupus-like nephritis, and were analyzed for renal Dnase1, MMP2 and MMP9 mRNA levels and for corresponding enzyme activities." (PMID 20041189, 2009). "Together, these findings suggest that MMP-9 may play an important role in both fibrosis and inflammation during the course of anti-GBM nephritis." (PMID 41341833, 2025). "Since nephritis does not appear at the same age in individual BW mice, instead of relating data to age, levels of Dnase1, MMP2 and MMP9 mRNA were combined for each mouse, and this set of data was sorted by descending Dnase1 mRNA levels." (PMID 20041189, 2009).
parasitic infections (9 papers, 2013 to 2025). "Our findings demonstrate that synovial parasitosis in osteoarthritic patients is not only influenced by host and therapeutic factors, such as corticosteroid use, but is also consistently associated with elevated inflammatory biomarkers (MMP-9 and TNF-α)." (PMID 41410796, 2025). "MMP-9 is implemented in nearly all parasitic infections for purposes of tissue remodeling and generally results in the downregulation of ECM syntheses such as collagen II and aggrecan." (PMID 36671243, 2022). "MMP-9 is part of MMPs family that involve in several neurological pathogenesis including parasitic infections, such as, protozoa and helminths." (PMID 32460746, 2020). "Although corticosteroid therapy (CST) may increase susceptibility to parasitic infection through suppression of immune surveillance, our findings showed elevated TNF-α and MMP-9 levels among patients with synovial parasitosis." (PMID 41410796, 2025). "Collectively, these findings highlight MMP-9 elevation as a robust biomarker signature associated with synovial parasitosis in osteoarthritic patients, independent of demographic or clinical host factors." (PMID 41410796, 2025). "Placental levels of MPO, MMP9, and PRTN3 all positively correlate with placental parasitemia as well as placental hemozoin bearing WBCs, suggesting that production is enhanced by chronic infection." (PMID 34737733, 2021). "sCD40L and MMP-9 are inflammation markers extensively studied in cardiac disease but there is no previous data regarding the soluble CD40L (sCD40L) during parasitic infections in humans." (PMID 23870715, 2013). "The termination of parasite infection restored the expression of these signaling proteins, which implies that the PI3-K and MAPK pathways participate in IGF-1 signaling to induce MMP-9 expression." (PMID 32972437, 2020). "The MMP-9/NGAL ratio in the kidneys, urine or serum samples of hosts with parasitosis has not been investigated yet." (PMID 34205319, 2021).
skin inflammation (9 papers, 2016 to 2025). "Network toxicology analysis indicated a low risk of these carboxylic acid compounds inducing skin inflammation, with certain compounds (e.g., 3-phenyllactic acid) potentially exerting positive effects on MMP9 and PPARγ." (PMID 40286213, 2025). "MMP-9 also cleaves extracellular matrix components and causes skin inflammation via activation of cytokines, including IL-1β and IL-1349." (PMID 35697899, 2022). "The anti-dermatitis activity of the aqueous extract of P. frutescens is, possibly, due to the downregulation of matrix metalloproteinase-9 (MMP-9) and IL-31 expression levels, and upregulation of T-bet activity." (PMID 35684514, 2022). "Therefore, if 3-phenyllactic acid can effectively inhibit MMP9 activity, it may potentially exert a positive effect on suppressing skin inflammation." (PMID 40286213, 2025). "Specifically, we observed attenuation of skin inflammation and a significant reduction in expression of mast cell mediators such as CCL2, IL-6, TNFα and MMP9 in the presence of osthole." (PMID 32391014, 2020). "The upregulation of MMP-9 and IL-2 after UVB induction may be closely related to skin inflammation and immune abnormalities." (PMID 40232010, 2025).
trachoma (9 papers, 2006 to 2024). "No SNP(PEMMAX < 0.01) was detected in any of thegenes IL8, IL10, CSF2, IFNG, HP, CCL8 or MMP9; all of which had beenpreviously reported to associate with trachoma." (PMID 26616738, 2015). "Scarring trachoma in adults is associated with increased expression of MMP9 and a coding SNP that is adjacent to the active binding site of the MMP9 enzyme." (PMID 23457650, 2013). "We genotyped 651 case-control pairs from trachoma endemic villages in The Gambia for coding single nucleotide polymorphisms (SNPs) in the MMP9 gene using the high-throughput Sequenom® system." (PMID 16643654, 2006). "IL-17A, CXCL5, PDGF, MMP7 and MMP9 have previously been associated with various stages of trachoma (trachomatous inflammation–follicular, TS and TT) at mRNA and protein expression levels, however they were not demonstrably up-regulated in TT cases in the present study." (PMID 27249027, 2016). "More recently, researchers found that heterozygosity for the Q279R polymorphism in matrix metalloproteinase 9 (MMP-9), which plays a role in tissue remodeling, was associated with lower risk for scarring trachoma compared to homozygosity for the “A” allele (i.e.Q279)." (PMID 18974840, 2008). "We tested the hypothesis that genetic variation in coding regions of MMP9 affects the risk of scarring sequelae of trachoma." (PMID 16643654, 2006). "This mutation, which leads to a nonsynonymous amino-acid change within the active site of the enzyme may reduce MMP-9-induced degradation of the structural components of the ECM during inflammatory episodes in trachoma and its associated fibrosis." (PMID 16643654, 2006). "Children with active trachoma have increased amounts of conjunctival MMP9 (determined by immunohistochemistry, zymography and gene expression analysis)." (PMID 24606636, 2014). "Children with active trachoma have increased amounts of MMP9 (determined by immunohistochemistry, zymography, and gene expression analysis)." (PMID 23457650, 2013). "There was some evidence for interaction between the MMP9 Q279R and IL8-251 alleles affecting risk of scarring trachoma (LRT χ2 = 4.14, p = 0.042)." (PMID 20015396, 2009). "MMP-9 expression and activity is up-regulated in the inflamed conjunctiva of trachoma subjects and increases with the severity of clinical inflammation." (PMID 16643654, 2006). "MMP-9 activity has been detected in immune cells present in the inflammatory infiltrate in conjunctival biopsy specimens from individuals with active trachoma." (PMID 16643654, 2006). "Immunohistochemistry (IHC) studies using tissue from a small number of individuals with active trachoma have shown that MMP9, CTGF, platelet derived growth factor (PDGF) and IL-1β were up-regulated in infiltrating monocytes/macrophages and that IL-1β was increased in the conjunctival epithelium." (PMID 27249027, 2016). "MMP9 in particular has been studied extensively in trachoma." (PMID 23457650, 2013). "A plausible explanation of these results is that Q279R represents a partial loss-of-function mutation within the proteinase whose presence reduces the development of fibrosis; these findings implicate MMP-9 as a key molecule in the pathogenesis of conjunctival scarring in trachoma." (PMID 16643654, 2006). "It is plausible that persistently increased MMP9 activity in the conjunctiva of subjects with trachoma may be a key event in the pathogenesis of conjunctival scarring through excessive degradation of ECM and fibrosis." (PMID 16643654, 2006). "This work supports the hypothesis that MMP-9 has a role in the pathogenesis of blinding trachoma." (PMID 16643654, 2006). "MMP7 has consistently been found to be upregulated in scarring trachoma and trichiasis alongside MMP9 and MMP12 but there is less evidence for a role of MMP7 in active trachoma." (PMID 28966918, 2017). "Expression and activity of matrix metalloproteinase 9 (MMP-9), a major effector of ECM turnover, is up-regulated in the inflamed conjunctiva of trachoma subjects." (PMID 16643654, 2006).
vitiligo (9 papers, 2022 to 2026). Generalized well circumscribed patches of leukoderma that are generally distributed over symmetric body locations and is due to autoimmune destruction of melanocytes. "MMP9 produced by keratinocytes in response to IFN-γ has been also implicated in melanocyte detachment from the basal epidermal layer in vitiligo skin." (PMID 38473275, 2024). "In vitiligo, a chronic hypomelanotic disorder, an increased presence of MMP9 is implicated with loss of melanocytes and associated hypopigmentation, via decreased expression of E-cadherin at the peri-lesional sites." (PMID 39602398, 2024). "Elevated levels of MMP-9, found in the skin and sera of vitiligo patients, contribute to the disruption of E-cadherin in the basal layer of the epidermis." (PMID 39201060, 2024). "In active disease the levels of MMPs, especially MMP-9, are elevated in the lesional skin of vitiligo patients under the influence of IFN-γ and TNF-α." (PMID 37275386, 2023). "Interestingly, E-cadherin levels are lower in vitiligo patients’ perilesional skin, whereas MMP-9 levels are higher in the skin and sera of patients with vitiligo." (PMID 35884944, 2022). "Notably, since the ability of melanocyte migration during re-pigmentation also largely depends on MMP9 activity, impaired MMP activity has been proposed to explain the reduced migration of melanocyte precursor from the outer root sheath in vitiligo skin." (PMID 38473275, 2024). "Type 1 cytokines IFN-γ and TNF-α induce melanocyte detachment via E-cadherin disruption and the release of its soluble form, possibly due to increased matrix metalloproteinase 9 (MMP9) in the skin and blood in vitiligo patients, contributing to vitiligo pathogenesis." (PMID 38673994, 2024).
acute lymphoblastic leukemia (8 papers, 2000 to 2025). Leukemia with an acute onset, characterized by the presence of lymphoblasts in the bone marrow and the peripheral blood. "Moreover, HDAC8, along with isoforms 1 and 6, was proven to increase invasion and MMP9 expression in breast cancer cells, and together with MMP2, is overexpressed in AML and acute lymphoblastic leukaemia (ALL)." (PMID 36077415, 2022).
aortic stenosis (8 papers, 2017 to 2025). Aortic valve stenosis is a aortic valve disease caused by the incomplete opening of the aortic valve. "For example, MMP-2 and MMP-14 levels robustly increase in LV pressure overload models and myocardial biopsies of aortic stenosis (AS), whereas the levels of MMP-14, MMP-7, MMP-8, and MMP-9 increase in end-stage dilated cardiomyopathy." (PMID 28484397, 2017). "Interestingly, they later identified matrix metalloproteinase 9 expression (MMP9), a mitochondrial-related gene, as being extremely high in AS samples, which would be a useful biomarker for aortic stenosis." (PMID 37446282, 2023). "In addition, serum MMP-9, but also MMP-3 and TIMP-1, was correlated with invasive aortic PWV measurements in patients with aortic stenosis." (PMID 29070037, 2017).
apical periodontitis (8 papers, 2012 to 2025). "They showed that MMP9 knockout mice experimentally induced with apical periodontitis suffered a more severe inflammation than wild type mice." (PMID 33144645, 2020). "In apical periodontitis, expression and activity of MMP-9 was found to be significantly higher than that in normal periodontal ligament tissue." (PMID 31166414, 2019). "Significant elevation of MMP9 expression was observed in apical periodontitis." (PMID 33144645, 2020). "Although it has been reported that MMP-9 knockout mice develop larger apical periodontitis than wild mice, those findings should be carefully interpreted since several MMPs might exert compensatory effect, colaborating with enhanced bone loss." (PMID 31166414, 2019). "In an animal study, MMP-9 and MMP-2 have a strong correlation with progression of apical periodontitis." (PMID 36012195, 2022). "MMP-9 and MMP-2 have been identified through immunohistochemistry in experimentally-induced apical periodontitis in animal models where they were proposed to play a role in both, the initiation and progression of apical periodontitis." (PMID 22436166, 2012). "In patients with apical periodontitis presented clinically by a negative sensibility test and apical radiolucency, MMP-9 is reduced by sodium hypochlorite and sodium hypochlorite limewater." (PMID 36012195, 2022). "Biomarkers of bone resorption in apical periodontitis including MMP-9 in controlled diabetic and normoglycemic patients are not significantly different." (PMID 36012195, 2022).
arteriosclerosis (8 papers, 2013 to 2025). A vascular disorder characterized by thickening and hardening of the walls of the arteries. "Toll-like receptor 4 (TLR4) and matrix metalloproteinase-9 (MMP-9) are known to play important roles in inflammatory diseases such as arteriosclerosis and plaque instability." (PMID 31001118, 2019). "Arteriosclerosis, a chronic inflammatory disease, is closely related to the overexpression of pro-inflammatory cytokines and MMP-9 of macrophages." (PMID 31001118, 2019). "As a proinflammatory factor, toll-like receptor 4 (TLR4) upregulates MMP9 expression and mediates inflammatory responses and also contributes to arteriosclerosis." (PMID 23844137, 2013). "We hypothesise that there are sex-specific relationships of GDF-15, YKL-40, MMP-9 with vascular outcomes (athero-/arteriosclerosis) and mortality in end-stage kidney disease (ESKD)." (PMID 34526107, 2021). "However, BMSC treatment in T1DM rats significantly increased vascular inflammatory response identified by increased Angiogenin, MMP9 and ED1 expression as well as increased arteriosclerosis-like vascular structure changes." (PMID 24303036, 2013).
B cell lymphoma (8 papers, 2007 to 2023). "In contrast, only a small fraction of the patients with exranodal marginal zone B-cell lymphoma of mucosa-associated lymphoid tissue type and follicular lymphomas expressed MMP9." (PMID 18093334, 2007). "In the body, demasking is mediated by proteases such as MMP-9 and matriptase described to be prognostic factors for B cell lymphoma when overexpressed." (PMID 37841262, 2023). "Further analyses revealed that alteration of the expression of signature genes by ColXV was associated with B-cell lymphoma family and ECM remodeling, especially Bcl-2, Col1a1, Col6a1, MMP-2 and MMP-9." (PMID 32024006, 2020). "The masking unit was genetically fused to the N-terminus of the anti-IgM light chain (LC) via a dual-protease cleavable linker addressable by matrix metalloproteinase-9 (MMP-9) and matriptase since these proteases are described to be overexpressed in B cell lymphoma." (PMID 37841262, 2023). "Higher MMP-9 protein and mRNA expression levels were observed in T-cell lymphomas compared to B-cell lymphomas and healthy control lymph nodes, indicating that MMP-9 may be associated with tumour phenotype." (PMID 23641796, 2013). "The immunocytochemical expression of MMP-9 was grade 3 in 16 T-cell lymphomas (13 HG and 3 LG) and grade 2 in the remaining T-cell lymphomas (5 LG), whereas in 21 B-cell lymphomas the expression was grade 1 (18 HG and 3 LG) and grade 2 in the remaining cases (4 HG and 1 LG)." (PMID 23641796, 2013). "Therefore, MMP-9 produced by B-cell lymphoma cells may also contribute to the increase of sIL-2R levels in sera." (PMID 24236041, 2013). "Further, K1 induces B-cell lymphomas in transgenic mice through constitutive Lyn kinase activation, crucial for the production of VEGF and NF-kB activation, and induces MMP-9 and VEGF secretion from epithelial and endothelial cell lines." (PMID 25592960, 2015). "In a previous work in dogs, we demonstrated that plasma levels of MMP-9 and VEGF are higher in B-cell and T-cell lymphomas with respect to healthy dogs and that their levels significantly decreased in B-cell lymphomas during chemotherapy." (PMID 23641796, 2013). "Higher mRNA and protein levels of MMP-9 and VEGF-A were observed in T-cell lymphomas than in B-cell lymphomas and healthy control lymph nodes." (PMID 23641796, 2013). "Significantly higher MMP-9 and TIMP-1 mRNA expression levels were observed in T-cell lymphomas compared to B-cell lymphomas and healthy controls (p<0.05)." (PMID 23641796, 2013). "The expressions of MMP-9, MT1-MMP, TIMP-1 and RECK were significantly higher in HG T-cell lymphomas compared to HG B-cell lymphomas (p<0.05)." (PMID 23641796, 2013). "The elevated levels of vitreous sIL-2R may be the result of the cleavage of IL-2R on the surface of T cells and B cell lymphoma cells with activated MMP-2 and MMP-9." (PMID 36357882, 2022). "IL-2R on T cells and B cell lymphoma cells are composed of α, β, and γ chains, and sIL-2R is a soluble form of the α chain of IL-2R, which is cleaved by matrix metalloproteinases (MMP)-2 and MMP-9." (PMID 36357882, 2022). "We also performed gelatine zymography in T-cell and B-cell lymphomas to investigate the activity of MMP-2 and MMP-9, but no catalytic activity was detected." (PMID 23641796, 2013). "Distant involvement free 5-year survival rates for patients with MMP-9 negative, and MMP-9 positive in B cell lymphomas were 100%, and 62%, respectively." (PMID 18093334, 2007). "Furthermore, all B-cell lymphoma cells, including intravascular B-cell lymphoma (IVL), were negative for MMP-9, while ATLL cells were positive for MMP-9." (PMID 24236041, 2013).